CD81 (CD81 molecule)
Diseases named in the same sentence as CD81 in open-access papers (continued):
Sharing a sentence is not in itself a finding about the gene and the disease.
bacterial infection (2 papers, 2020 to 2024). "There is also growing evidence for roles for tetraspanins in bacterial infection; for example, CD81 has been demonstrated to be involved in Listeria monocygenes invasion into human epithelial cells." (PMID 33087788, 2020).
metabolic disease (2 papers, 2021 to 2023). A congenital disorder (due to inherited enzyme abnormality) or acquired (due to failure of a metabolically important organ) disorder resulting from an abnormal metabolic process. "The authors did not examine a role for CD81+ sEVs in this study, and it is not yet known how metabolic disease influences the circulating abundance and trafficking of CD81+ sEVs." (PMID 37753183, 2023). "CD81 is also known to interact with integrin receptors that not only regulate cellular behavior, but are also involved in metabolic disease etiology." (PMID 37753183, 2023).
inflammation (1 paper, 2020). Aberrant reaction of the microcirculation characterized by movement of fluid and leukocytes from the blood into extravascular tissues. "Thus, the anti-CD81 antibody had therapeutic effects on DSS-induced acute intestinal inflammation." (PMID 32332834, 2020).
CD81 also shares sentences with these, for which no sentence is quoted: Insulin resistance (5 papers); liver cancer (4); Alzheimer disease (3); brain tumor (3); adenocarcinoma (2); ganglioneuroblastoma (2); Glucose intolerance (2); head and neck cancer (2); Hepatitis (2); metastatic cancer (2); non-small cell carcinoma (2); Pleural effusion (2); viral disease (2); adrenal carcinoma (1); alloimmunization (1); anemia (1); asthenozoospermia (1); benign kidney tumor (1); benign tumors (1); carcinoma in situ (1); cardiac disease (1); cardiac hypertrophy (1); cervical cancer (1); Chagas disease (1); co-infection (1); colonic adenocarcinoma (1); colorectal (1); demyelination (1); dengue (1); Down syndrome (1).
A further 44 diseases each share a sentence with CD81 in 1 paper.